SNORD43 (small nucleolar RNA, C/D box 43)
Synonyms: U43; RNU43
Gene: Small nucleolar RNA gene on chromosome 22 (39,319,050 to 39,319,113, reverse strand). Ensembl gene ENSG00000263764.
Gene Ontology:
Biological process: RNA processing
Cellular component: nucleolus
Homologues: Orthologues: chimpanzee SNORD43 (100% identical), macaque SNORD43 (98% identical), pig SNORD43 (98% identical), guinea pig SNORD43 (95% identical), rat Snord43 (84% identical), rabbit SNORD43 (81% identical).
Diseases named in the same sentence as SNORD43 in open-access papers:
SNORD43 is named in the same sentence as 6 diseases in open-access papers, as found by Europe PMC text mining. Sharing a sentence is not in itself a finding about the gene and the disease. The quoted sentences say what the papers report.
cancer (2 papers, 2011 to 2021). A tumor composed of atypical neoplastic, often pleomorphic cells that invade other tissues. "SNORD43 is one of the four snoRNAs that has been reported as dysregulated in cancer." (PMID 34806414, 2021).
SNORD43 also shares sentences with these, for which no sentence is quoted: breast tumours (1 paper); infection (1); leukemia (1); prostate carcinoma (1); tumours (1).